RAG1 (recombination activating 1)
Description:
Catalytic component of the RAG complex, a multiprotein complex that mediates the DNA cleavage phase during V(D)J recombination. V(D)J recombination assembles a diverse repertoire of immunoglobulin and T-cell receptor genes in developing B and T-lymphocytes through rearrangement of different V (variable), in some cases D (diversity), and J (joining) gene segments. In the RAG complex, RAG1 mediates the DNA-binding to the conserved recombination signal sequences (RSS) and catalyzes the DNA cleavage activities by introducing a double-strand break between the RSS and the adjacent coding segment. RAG2 is not a catalytic component but is required for all known catalytic activities. DNA cleavage occurs in 2 steps: a first nick is introduced in the top strand immediately upstream of the heptamer, generating a 3'-hydroxyl group that can attack the phosphodiester bond on the opposite strand in a direct transesterification reaction, thereby creating 4 DNA ends: 2 hairpin coding ends and 2 blunt, 5'-phosphorylated ends. The chromatin structure plays an essential role in the V(D)J recombination reactions and the presence of histone H3 trimethylated at 'Lys-4' (H3K4me3) stimulates both the nicking and haipinning steps. The RAG complex also plays a role in pre-B cell allelic exclusion, a process leading to expression of a single immunoglobulin heavy chain allele to enforce clonality and monospecific recognition by the B-cell antigen receptor (BCR) expressed on individual B-lymphocytes. The introduction of DNA breaks by the RAG complex on one immunoglobulin allele induces ATM-dependent repositioning of the other allele to pericentromeric heterochromatin, preventing accessibility to the RAG complex and recombination of the second allele. In addition to its endonuclease activity, RAG1 also acts as an E3 ubiquitin-protein ligase that mediates monoubiquitination of histone H3. Histone H3 monoubiquitination is required for the joining step of V(D)J recombination. Mediates polyubiquitination of KPNA1 (By similarity).
Synonyms: RAG-1; RNF74; MGC43321
Tractability: PROTAC: UniProt records ubiquitination sites on it; ubiquitination databases record sites on it.
Gene: Protein-coding gene on chromosome 11 (36,510,372 to 36,593,156, forward strand). Ensembl gene ENSG00000166349.
Subcellular location: Nucleus
Subcellular location (Human Protein Atlas): Nucleoplasm; Nucleoli
Pathways (Reactome):
Immune System: Interleukin-7 signaling
Signal Transduction: MAPK6/MAPK4 signaling
Gene Ontology:
Molecular function: protein binding; DNA binding; double-stranded DNA endonuclease activity; endonuclease activity; histone binding; metal ion binding; protein homodimerization activity; sequence-specific DNA binding; ubiquitin protein ligase activity; ubiquitin-protein transferase activity; zinc ion binding; identical protein binding
Biological process: V(D)J recombination; adaptive immune response; B cell differentiation; DNA recombination; immune response; pre-B cell allelic exclusion; protein autoubiquitination; T cell differentiation in thymus; positive regulation of T cell differentiation; regulation of behavioral fear response; visual learning
Cellular component: DNA recombinase complex; endodeoxyribonuclease complex; nucleoplasm; nucleus
Genetic constraint (gnomAD): Loss-of-function variants: 35 observed, 65.98 expected, observed/expected ratio (o/e) 0.53, 90% interval 0.4 to 0.7. The upper end of that interval is the gene's LOEUF score, 0.7, which puts it in group 2 of 6, group 1 being the genes least tolerant of losing a copy. Missense variants: 1,169 observed, 1,348 expected, observed/expected ratio (o/e) 0.87, 90% interval 0.83 to 0.91. Synonymous variants: 461 observed, 498.63 expected, observed/expected ratio (o/e) 0.92, 90% interval 0.86 to 1.
Gene-disease validity (ClinGen):
ClinGen rates the evidence that RAG1 causes each of these diseases.
recombinase activating gene 1 deficiency (autosomal recessive): Definitive. A severe combined immunodeficiency that is the result of a mutation on Chromosome 6 RAG1 gene involving genetic rearrangement of both the T- and B-lymphocyte receptor genes.
Homologues: Orthologues: macaque RAG1 (98% identical), rabbit RAG1 (93% identical), pig RAG1 (92% identical), guinea pig RAG1 (90% identical), rat Rag1 (90% identical), mouse Rag1 (90% identical), chimpanzee RAG1 (90% identical), dog RAG1 (84% identical), tropical clawed frog RAG1 (72% identical), zebrafish rag1 (59% identical).
Diseases named in the same sentence as RAG1 in open-access papers:
RAG1 is named in the same sentence as 279 diseases in open-access papers, as found by Europe PMC text mining. Sharing a sentence is not in itself a finding about the gene and the disease. The quoted sentences say what the papers report.
colitis (178 papers, 2008 to 2026). Inflammation of the colon. "Rag1−/− recipients of CD45Rbhi T cells and Areg‐deficient Tregs developed more severe colitis compared to Rag1−/− recipients of CD45Rbhi T cells and WT Tregs." (PMID 41178490, 2026). "In contrast, Rag1–/– mice that received Bcl‐3‐deficient T cells were protected from transfer‐induced colitis." (PMID 40359334, 2025). "Transgenic mice expressing tumor necrosis factor induced protein 3 (TNFAIP3; aka A20) in intestinal epithelial cells under the villin promoter (v-TNFAIP3) develop colitis on the recombination activating 1 (RAG1) deficient background (v-TNFAIP3 x RAG1-/-)." (PMID 38512959, 2024). "Here we report that CR infection causes severe colitis and mortality in interleukin 22 knockout (Il22-/-) and Rag1 knockout (Rag1-/-) mice under germ-free (GF) conditions." (PMID 39630719, 2024). "Here, we found that GzmbB-deficient CD4+ T cells induced more severe colitis in Rag1-/- mice than wild-type (WT) CD4+ T cells." (PMID 38841892, 2024). "Based on flow cytometry, colitis‐associated Th17 cells are the target of L. intestinalis, which is supported by the lack of protective effects of L. intestinalis in T cell‐null Rag1−/− mice or upon anti‐IL‐17‐A antibody‐treated mice." (PMID 37983567, 2023). "One such model is adoptive transfer of naïve T cells into Rag1-deficient mice to induce experimental colitis (T-cell transfer model of chronic colitis, from here on referred to as transfer colitis)." (PMID 37024677, 2023). "Adoptive transfer of WT CD4+ T cells into TSLPR-deficient Rag1KO mice (Rag1–/–Tslpr–/– or Rag1KOTslprKO) caused fulminant, lethal colitis." (PMID 37427591, 2023). "Adoptive transfer of T cells deficient in Th17-associated cytokines (IL-17A, IL-17F, and IL-22) into Rag1 knockout mice induced severe colitis comparable to that induced by wild-type cells." (PMID 37239894, 2023). "DSS-colitis can be induced in immunodeficient mice including recombination-activating gene (RAG)-1-deficient and severe combined immune deficient (SCID) mice, suggesting the dispensability of the adaptive immune system in initiating disease." (PMID 36012618, 2022). "Mice expressing tumor necrosis factor-induced protein 3 (TNFAIP3) in intestinal epithelial cells (villin-TNFAIP3) develop colitis when interbred with Recombination Activating 1-deficient mice (RAG1−/−)." (PMID 36162004, 2022). "When activated ILC1s and ILC3s were adoptively transferred into DSS-induced colitis Rag1-/-Il2rg-/- (ILCreg deficient) mice, severe colitis resulted, an effect that was attenuated upon ILCreg reconstitution." (PMID 36275689, 2022). "Adoptively transferred TNFR2-deficient Tregs were unable to confer protection from colitis induced by co-transferred Teffs in Rag1 KO mice, underlining the critical role of TNFR2 in Treg phenotypic and functional stability in inflammatory environments." (PMID 36466853, 2022). "A population of CD4+IL-17F+ T cells was sufficient to induce colitis in RAG1-deficient recipients, where the transition of these precursors to Th1-like cells was an absolute requirement for disease." (PMID 36012618, 2022). "Rag1-deficient (−/−) mice were injected with 5 × 105 naïve T cells (CD3+CD4+CD45RBHi) to induce colitis." (PMID 34572293, 2021). "The relative low number of total T cells containing a mixture of naïve/memory and CD4/CD8 T cells were transferred into recipient mice which were insufficient to cause colitis in B6 Rag1-/- recipients." (PMID 34950143, 2021). "In mouse of the Rag1−/− background, Brg1 limits the homeostatic expansion of ILC3s and suppresses the pathogenicity of ILC3s to cause colitis by inhibiting GM-CSF production." (PMID 32612160, 2021). "We found that Rag1−/−Smarca4ΔILC3 mice developed spontaneous colitis at 6–8 weeks of age, which was caused by enhanced production of GM-CSF from Brg1-deficient ILC3s." (PMID 32612160, 2021).
colitis (continued). "To further confirm the pharmacological effects of NEt-3IB, we also evaluated the progressive bodyweight loss and diarrhea in a similar colitis model using Rag1−/− mice as a recipient." (PMID 34475823, 2021). "Rag1-deficient mice receiving these butyrate-treated T cells showed less severe colitis compared with animals receiving untreated T cells." (PMID 34249014, 2021). "To explore this in vivo, we used a mouse model of inflammatory bowel disease where transfer of naive CD4+ T cells into RAG1-deficient mice, which lack their own lymphocytes, drives colitis." (PMID 34216540, 2021). "HIF-1α-KO tTreg cells (Cd4CreHif1af/f) were as effective as Hif2af/f tTreg cells in suppressing colitis and associated pathologies in RAG-1-KO mice receiving effector T cells." (PMID 33024109, 2020). "When we transferred Mettl14-deficient Treg cells with the WT naïve T cells into the Rag1–/– mice, the Mettl14-deficient Treg cells were unable to suppress naïve T cell–induced colonic inflammation." (PMID 32634481, 2020). "Employing the CD4+CD25− naïve T cell transfer model, we found that T cells fail to elicit colitis in IRF4-deficient compared to IRF4-proficient Rag1−/− mice." (PMID 33584655, 2020). "The second reason is that although DSS-induced intestinal damage can happen in CD4 T cell depletion/deficient condition, the severity of colitis was dramatically decreased in Rag-1 KO mice compared with that in WT mice." (PMID 32183814, 2020). "Here, we show that adrenergic receptor activation has a potent anti-inflammatory effect on murine macrophages and that abrogation of sympathetic innervation to the intestine causes innate immune driven colitis in Rag1−/− mice." (PMID 30616543, 2019). "Thereby, our and other groups used genetically susceptible colitis mouse models (Rag1-, IL-2-, and IL-10-deficient) exhibiting a dysregulated immune system to mimic disease development in an immune suppressed host." (PMID 32038631, 2019). "Adoptive transfer of IL-17A-, IL-17F-, or IL-22-deficient T lymphocytes into RAG1-null mice results in more severe colitis than that caused by wild-type T cells." (PMID 30804707, 2019). "A recent study reported that AHCC® supplementation (75 mg/day) improved lymphocyte-driven colitis in recombination activating gene 1- (RAG-1-) deficient mice transferred with CD4+CD62L+ T cells." (PMID 31930148, 2019). "Colitis was induced in recombinase activating gene-1 deficient (Rag1-/-) mice injected with syngeneic CD4+CD62L+ naïve T cells." (PMID 31212794, 2019). "We utilized a well-established mouse model of colitis in Rag1-deficient mice, which was induced by adoptive transfer of normal CD4+CD45RBhigh T cells." (PMID 30971739, 2019). "We then divided the splenic IL-10-producing Foxp3neg CD4+ T cells, which promoted colitis when transferred as one population in Rag1 deficient mice, into CIR rich and CIR poor cells and tested their pathogenicity in vivo." (PMID 30575716, 2018). "The transfer colitis model into recombination-activating gene 1 (Rag1−/−)-deficient recipients which lack T and B cells was used." (PMID 28779026, 2018). "Was-deficient innate immune cells were also suggested to exacerbate colitis after the observation that the transfer of WT naïve CD4 T cells in Was/Rag1 double-deficient mice induced a more severe colitis compared to their transfer into Rag1-deficient mice." (PMID 30410494, 2018). "Having found a critical role for Alpk1 in regulating inflammation in a Rag1-deficient setting, we next assessed its impact on lymphocyte-replete colitis." (PMID 30228258, 2018). "To test which effector cytokines were required for colitis induced by T-bet-deficient T cells, we transferred cohorts of Rag1−/− recipients with WT or Tbx21−/− T cells and administered neutralizing antibodies to IL-17A or IL-22." (PMID 27193261, 2016). "When colitis was induced in Rag1-deficient mice, recipients of either wild type or Tpl2−/− naïve CD4 T cells experienced similar weight loss kinetics." (PMID 25781948, 2015).
colitis (continued). "Surprisingly, β2i/MECL-1−/−β5i/LMP7−/− CD4+ T-cells also caused colitis, both in RAG1−/− and RAG1−/−β2i/MECL-1−/−β5i/LMP−/− mice." (PMID 24740379, 2014). "To further investigate the role of proteasome immunosubunits in autoimmune, inflammatory disease, we analyzed T-cell-induced colitis development in RAG1 gene-deficient mice compared to RAG1&β2i/MECL-1&β5i/LMP7-deficient mice, in a T-cell transfer model." (PMID 24740379, 2014). "We show that naïve CD4+ T-cells of mice that lack the two immunosubunits β2i/MECL-1&β5i/LMP7 cause colitis upon transfer into RAG1−/− mice, which is more severe than colitis induced by transfer of naïve wt CD4+ T-cells." (PMID 24740379, 2014). "Naïve wt or immunosubunit-deficient CD4+ T-cells were adoptively transferred into RAG1−/− and immunosubunit-deficient RAG1−/− mice and colitis development was determined six weeks later." (PMID 24740379, 2014). "Even when rag1−/− mice are colonized with Citrobacter rodentium which typically causes colonic hyperplasia in mice, the acute phase granulocyte based colitis was transient and by 21 days returned to normal, despite increasing numbers of colonizing bacteria." (PMID 22783255, 2012). "Adoptive transfer of splenic GMPs isolated from colitic mice into Rag1−/− mice that had received naive T cells 2 weeks before enhanced disease as indicated by an increased colitis score and weight loss." (PMID 23200826, 2012). "Two models of IBD were employed: i) chemical-induced colitis primarily mediated by innate immune cells; and ii) colitis initiated by CD4+CD45RBhigh T cells following their transfer into immuno-deficient RAG1-/- hosts." (PMID 21533159, 2011). "Notably, both Atg7ΔCD4 mice that induced by TNBS rectal administration and Atg7ΔCD4CD45RBhighCD4+ T cell‐reconstituted Rag1−/− mice, displayed more severe colitis, suggesting that Atg7 deficiency disrupts Th1/Treg cell‐mediated mucosal immunity." (PMID 40887825, 2025). "Indeed, the in vivo suppression assay using immune-deficient Rag1−/− mice clearly showed that very severe colitis, induced by injection of naive CD4+-T cells, cannot be inhibited by Ube2m-deficient Treg cells." (PMID 35641500, 2022). "Protective actions could be seen in a study where DCs, when stimulated with TLR9 agonists, produced type I IFNs leading to the protection against experimental colitis in RAG1-deficient mice." (PMID 34249014, 2021). "The adaptive cell transferred model (e.g., CD4+CD45RBhigh T cells) is one of the models to mimic chronic colitis in which naive T cells from immunoactivity mice are transferred to T - and B-deficient hosts (e.g., Rag1/2 -/- or SCID mice) to induce colonic inflammation." (PMID 34956195, 2021). "Furthermore, in both wild-type and Rag1–/– mice, the exacerbation of colitis in α-DR3-treated group was accompanied by loss of ILC3s." (PMID 31358760, 2019). "The passive transfer of naïve cytochrome p450 family 26 subfamily b1-deficient (Cyp26b1−/−) mice CD4 T cells into recombination-activating gene 1-deficient (Rag1−/−) mice resulted in a significantly reduced disease state in a model of T cell-dependent colitis." (PMID 30158832, 2018). "To assess whether JunB is also required for other TH17-mediated diseases, we investigated the function of JunB in colitis development by transferring Junb-deficient CD4+CD45RBhiCD25− T cells into Rag1-deficient mice." (PMID 28555647, 2017). "Consistent with normal levels of Foxp3 in the recovered Tregs, Hif1a-knockout re-established the ability of Dtx1−/− tTregs to repress CD4+CD25− T cell-induced colitis in Rag1−/− mice as determined by colitis score readout, body weight loss and intestinal morphology." (PMID 25695215, 2015). "Thus, in the T-cell transfer model, β2i/MECL-1&β5i/LMP7-deficiency in transferred, naïve CD4+ T-cells enhances colitis development in RAG1−/− mice, whereas immunosubunit-deficiency in the targeted gut does not have any effect on colitis development." (PMID 24740379, 2014).